XKRYP7 (XK related, Y-linked pseudogene 7 )
Synonyms: XKRY2
Gene: Long non-coding RNA gene on chromosome Y (18,135,449 to 18,137,029, forward strand). Ensembl gene ENSG00000290725.
Homologues: Paralogues in human: XKRY (100% identical).